FGF10 (fibroblast growth factor 10)
Diseases named in the same sentence as FGF10 in open-access papers (continued):
Sharing a sentence is not in itself a finding about the gene and the disease.
LADD syndrome (9 papers, 2008 to 2022). A multiple congenital anomaly syndrome characterized by hypoplasia, aplasia or atresia of the lacrimal system; anomalies of the ears and hearing loss; hypoplasias, apalsias or atresias of the salivary glands; dental anomalies and digital malformations. "List of the coding variants within FGF10 identified in patients with lethal lung developmental disorders, lacrimo-auriculo-dento-digital syndrome, and aplasia of the lacrimal and salivary glands." (PMID 36124135, 2022). "Single-nucleotide variants in FGF10 or FGF10-involving copy-number variant deletions have been reported in families with lacrimo-auriculo-dento-digital syndrome, aplasia of the lacrimal and salivary glands, or lethal lung developmental disorders." (PMID 36124135, 2022). "Loss of Fgf10 resulted in smaller, malformed pinnae, correlating with the dysmorphisms found in LADD syndrome, in which patients show smaller, cup-shaped ears." (PMID 33363172, 2020). "The Fgf10 knockout mouse can therefore be used as a model to study the mechanisms underlying the pinna defect in LADD syndrome patients, and other syndromes with low set, cup shaped ears." (PMID 33363172, 2020). "For example, loss-of-function mutations in FGF10 have been reported to cause LADD (Lacrimo-auriculo-dento-digital) syndrome, which affects multiple organs, the majority of which are in the craniofacial complex." (PMID 30505318, 2018). "LADD syndrome is caused by mutations in one copy of Fgfr2b or Fgf10, therefore the heterozygous mice are a good model for this disorder." (PMID 27590203, 2016). "Sequence alterations in the intracellular tyrosine-kinase domains of FGFR2 and FGFR3 were described to be involved in LADD syndrome, and aberrations of the FGF10 gene were found to be associated with both the ALSG and the LADD syndrome." (PMID 19102732, 2008). "Similar defects might be present also in humans and explain a part of the phenotype LADD syndrome caused by mutations in FGF10 or FGFR2." (PMID 30505318, 2018). "In addition, the LADD syndrome is also caused by FGF10 mutations indicating that both syndromes are allelic disorders and part of the same phenotypic spectrum." (PMID 19102732, 2008). "In this study we have investigated pinna development in Fgf10 knockout mice in order to understand potential mechanisms involved in LADD syndrome." (PMID 33363172, 2020). "LADD syndrome has been shown to be caused by defects in the FGF (fibroblast growth factor) signaling pathway, with mutations in FGF10 and its receptor FGFR2b, both leading to the same phenotype." (PMID 33363172, 2020). "The two most familiar conditions associated with human FGF10 mutations are autosomal dominant aplasia of lacrimal and salivary glands (ALSG) and lacrimo-auriculo-dento-digital syndrome (LADD), with both conditions lacking a primary lung complication." (PMID 30930931, 2019). "In contrast, for LADD syndrome patients two FGF10 missense alterations were found which result in the exchange of less conserved residues suggesting residual or possibly altered activity of the aberrant protein." (PMID 19102732, 2008). "In humans, disruption of FGF10-FGFR2IIIb signaling causes a range of complex developmental disorders including cleft lip/palate, autosomal dominant aplasia of lacrimal and salivary glands (ALSG) and lacrimo-auriculo-dento-digital (LADD) syndrome." (PMID 29361553, 2018). "LADD syndrome is an autosomal dominant disorder caused due to mutations in one of at least three genes, the fibroblast growth factor receptor 2 (FGFR2), fibroblast growth factor receptor 3 (FGFR3), and fibroblast growth factor 10 (FGF10)." (PMID 27803819, 2016).
lung carcinoma (9 papers, 2011 to 2025). "Previous studies have shown that FGF10 secreted by tumor-associated macrophages (TAMs) are able to boost the growth of lung cancer, but the detailed mechanisms behind this enhancement remain unclear now." (PMID 35668376, 2022). "Another study revealed that FGF10 from mesenchyme-derived mesenchymal stromal cells preferentially activates the epithelial-type FGFR1b of lung cancer cells, resulting in the reduction of cancer stem cells." (PMID 31958320, 2020). "Analysis of 1144 lung cancer tumors comprising lung adenocarcinomas and lung squamous cell carcinomas revealed FGF10 amplifications in 8.7% and FGFR1 amplifications in 9.3% of cases." (PMID 30405704, 2018). "FGF2, FGF9 and FGF10 can stimulate proliferation, treatment sensitivity, and apoptosis of lung cancer cells." (PMID 27166269, 2016). "Our analysis reveals that eight lung cancer patients contain DNA amplification in the chr5:42,891-44,452 KB regions, including FGF10." (PMID 21569311, 2011). "Similarly, FGF10 has also been reported to play an essential role in the occurrence and progression of lung cancer and its overexpression in respiratory epithelial cells can easily lead to the occurrence of multifocal pulmonary adenocarcinoma." (PMID 35668376, 2022). "FGF10, a secreted factor, stimulated the proliferation of lung cancer cells." (PMID 35280778, 2022). "The role of FGF10 in lung cancer initiation and progression remains poorly understood." (PMID 30405704, 2018). "Consistent with the transcriptome data, SERPINE2 was more highly expressed in lung cancer tissues compared with that in paratumor tissues, while a low expression of FGF10, LSAMP, and PDE5A was found in lung cancer tissue." (PMID 37280069, 2023). "Previously, the mRNA expression of FGF10 in the fetal lung of mice was shown to disrupt lung morphogenesis, and the alternation of FGF pathways frequently occurs in lung cancer." (PMID 21569311, 2011). "For lung cancer samples, the base OncoPro medium formulation was supplemented with HS FGF-10, while medium for breast and endometrial cancer tumoroids was supplemented with HS FGF-10 and beta-estradiol." (PMID 39890889, 2025). "Also, the application of this approach to a lung cancer data set identifies focal amplification regions that contain known oncogenes, though these regions are not reported using a recent CNAs detecting algorithm GISTIC: SMAD7 (chr18q21.1) and FGF10 (chr5p12)." (PMID 21569311, 2011).
hypospadias (8 papers, 2013 to 2026). Hypospadias is the displacement of the urethral meatus on the ventrum of the penis. "On the other hand, a mutation in murine Fgf10 results in a hypospadias-like phenotype." (PMID 23390542, 2013). "For example, MAFB, FGF10, and FGFR2 are genes critical for urethral closure in both humans and mice, with mutations resulting in severe hypospadias." (PMID 41596366, 2026). "Deletion of Fgf10 or Fgfr2IIIb leads to severe hypospadias in mice, in which the ventral side of the urethra is fully open, resembling a urethral groove in guinea pigs, but still with the malformed prepuce." (PMID 40072077, 2025). "The results show decreased expressions of Shh, Bmp4, Fgf8, Fgf10 and Fgfr2 in the genital tubercle in male rats with hypospadias." (PMID 39728417, 2024). "In patient 5, six variants in six genes were found: BNC2, FGF10, HSD3B2, IRX5, MAML2 and NOTCH2; all, except MAML2, have also been associated with hypospadias or gonadal development." (PMID 31555317, 2019). "Fgf8, Fgf10, and their receptor Fgfr2 were identified as candidate genes for human hypospadias." (PMID 40072077, 2025). "Several FGF genes, including FGF8, FGF10, and fibroblast growth factor receptor 2 (FGFR2), were found to be expressed in the foreskin of children with hypospadias." (PMID 40072077, 2025).
injury (8 papers, 2020 to 2026). Damage inflicted on the body as the direct or indirect result of an external force, with or without disruption of structural continuity. "An LPS‐induced mouse model of acute lung injury (ALI) was used to evaluate the effects of FGF10 treatment in vivo." (PMID 41482636, 2026). "FGF10 has been shown to mitigate lung-specific inflammation resulting from traumatic or infectious lung injury." (PMID 39436561, 2024). "We used a non-specific PI3 kinase inhibitor, 3-MA, to further explore the relationship between FGF10 and autophagy in acute lung injury." (PMID 36618911, 2022). "The vagus nerve deploys α7nAChR to enhance LSCs proliferation and transdifferentiation and promote lung repair in an FGF10-dependent manner during LPS-induced lung injury." (PMID 32522255, 2020). "During lung development, FGF7 and FGF10 stimulate epithelial cell proliferation and distal alveolar development, respectively, and are able to promote lung repair of the adult lung after acute lung injury." (PMID 35675358, 2022). "One study showed that FGF10 could prevent or reduce lung-specific inflammation/ fibrosis due to traumatic or infectious lung injury." (PMID 34383782, 2021).
myopia (7 papers, 2019 to 2025). "In a cohort of 1,160 children and adolescents (ages 2–17), IGF1 rs5742714 was linked to myopia in children under 6, while FGF10 rs339501 was associated with moderate and mild myopia in children aged 6–1215." (PMID 40410244, 2025). "Abnormalities involving FGF10 have also been implicated in cleft lip and palate, myopia, or congenital heart disease." (PMID 36124135, 2022). "Pathogenic variants in FGF10 can cause craniofacial defects, lung disorders, myopia, limb or genitourinary system anomalies, and heart defects." (PMID 36124135, 2022). "Four singles nucleotide polymorphisms (SNPs) in the FGF10 gene (including rs1384449, rs339501, rs12517396 and rs10462070) were found to be associated with extreme myopia (EM, refractive error ≤ − 10.0 diopters) in Japanese and Chinese Taiwan population." (PMID 31687416, 2019). "Researchers indicate that PAX6 rs644242, ZC3H11B rs4373767 and BICC1 rs7084402, VIPR2 rs885863 and rs6979985, ZMAT4 rs7829127, TNKS rs4840437 and rs6989782, PDGFRA rs2114039, SOX2 rs4575941, FGF10 rs339501, rs2973644, and rs 79002828 are associated with severe myopia (moderate and extreme myopia)." (PMID 38660258, 2024). "The defect in FGF10 led to the development and differentiation of several ocular tissues, and FGF10 modulated extracellular matrix-associated genes that were involved in the development of myopia." (PMID 33644046, 2021). "Associated with FGF10, FGF7 has been confirmed to regulate specific mesenchymal-epithelial transition pathologically associated with extreme high myopia, validating our prediction." (PMID 40110040, 2025). "For example, the form-deprivation myopia (FDM) mouse model was used to demonstrate an increasing mRNA expression of FGF10 in FDM-treated eyes, suggesting that FGF10 can be considered a candidate gene for myopia." (PMID 31687416, 2019). "Furthermore, to avoid filtering real myopia genes, the role of FGF10 in the pathogenesis of myopia requires more refinement in both animal models and human genetic epidemiologic studies." (PMID 31687416, 2019). "Previous study also showed that retinoic acid could affect the development of myopia by regulating TGF-β pathway and the expression of FGF10." (PMID 31687416, 2019).
craniosynostosis (6 papers, 2009 to 2023). Craniosynostosis is defined as the premature fusion of one or more cranial sutures leading to secondary distortion of skull shape resulting in skull deformities with a variable presentation. "Fgf10 was selected as a candidate for further analysis as it has previously been shown to be expressed early in calvarial development and has been implicated in craniosynostosis pathogenesis." (PMID 32662771, 2020). "Based on these findings, we suggest that increased Fgfr2IIIb/Fgf10 expression contributes to the onset of craniosynostosis in AS mice." (PMID 25003957, 2014). "Also, the genetic knockdown of FGF10 is related to skeletal phenotypes such as craniosynostosis in a mouse model, and FGF18 is expressed during osteoblast differentiation." (PMID 35980984, 2022). "Hypomorphic Fgf-10 mutations have been shown to cause lacrimo-auriculo-dento-digital (LADD) syndrome-like defects in both mice and humans, and FGF-10 has been implicated in the development of craniosynostosis." (PMID 19410332, 2009). "Functional anomalies in FGF10 signals may be involved in craniosynostosis, but there are no obvious effects of FGF10 in our rat (unpublished data) and mouse calvaria cells." (PMID 25873956, 2015).
Pulmonary hypoplasia (6 papers, 2018 to 2021). "The emergence of rare coding variants involving FGF10 with putative hypomorphic noncoding SNVs implies a complex inheritance of pulmonary hypoplasias." (PMID 34204341, 2021). "Decreased expression of Fgf10 was reported in rodents nitrofen-induced pulmonary hypoplasia, furthermore exogenous Fgf-10 during fetal lung development in mice increased branching of nitrofen-exposed lungs." (PMID 29732364, 2018). "Corroboratively, homozygous Fgf10 knockout is neonatal lethal due to complete disruption of branching morphogenesis and heterozygous SNVs or CNV deletions involving FGF10 on 5p12 have been found in newborns with AcDys, CAD, or other pulmonary hypoplasias." (PMID 33478486, 2021).
breast tumors (5 papers, 2011 to 2022). "The aim of our study was to gain new insights into the role of private somatic mutations in FGFR2 and FGF10 in breast tumor development." (PMID 23527311, 2013). "We hypothesized that specific private mutations of an activating nature in FGFR2 and FGF10 might influence breast tumor development and growth." (PMID 23527311, 2013). "This process is affected by the activity of granzyme B, but at the same time FGF10 shows a positive regulatory effect on granzyme B, which ultimately leads to the enhancement of breast tumor invasion and migration ability." (PMID 35668376, 2022). "The SNP1 rs10941679 risk-associated g-allele was moderately associated with increased FGF10 mRNA expression in NBCS normal breast (p = 0.013, p corrected = 0.39) and breast tumors (p = 0.005, p corrected = 0.38) as well as in GTEx normal breast (p corrected = 0.02)." (PMID 27640304, 2016). "It has been known for many years that FGF8 and FGF10, both ligands for FGFR2, are overexpressed in human breast tumors, suggesting that antibodies to screen for active FGFR2 would be very useful." (PMID 23343422, 2013). "FGFR2 and FGF10, the main ligand of FGFR2, are both overexpressed in 5–10% of breast tumors." (PMID 23527311, 2013). "Unequivocal evidence that paracrine FGF released from breast tumor stroma functions to promote tumorigenesis is lacking, but, intriguingly, we found a strong correlation between FGFR2 and FGF10 mRNA expression levels in the cultured skin fibroblasts." (PMID 21767389, 2011).
colon cancer (5 papers, 2015 to 2024). "Noteworthy, an increased expression of FGF-10, VEGFC, IL-10 and TNFα of AMSCs was found to be along with an elevated EMT gene expression of colon cancer cells in the co-culture model in this study." (PMID 26060426, 2015). "To investigate the effect of VP on human colon cancers, we successfully modeled organoids from patients with colon cancer in a medium supplemented with the growth factors noggin, epidermal growth factor (EGF), human fibroblast growth factor 10 (FGF-10), HEPES, GlutaMAX, Y-27632, and A83-01." (PMID 34055773, 2021). "In colon cancer, MSCs enhance stemness and epithelial–mesenchymal transition through interleukin-8 (IL-8)/CXC chemokine receptor 2 (CXCR2)/mitogen-activated protein kinase (MAPK) and fibroblast growth factor 10 (FGF10)–protein kinase A (PKA)–protein kinase B (Akt)–β-catenin signaling pathways." (PMID 39624211, 2024).
cyst (5 papers, 2011 to 2024). A sac-like closed membranous structure that may be empty or contain fluid or amorphous material. "Thus, the loss of Yy1 expression in lung epithelium directly impacts Shh gene expression, resulting in increased FGF10 signaling that may play a causative role in defective branching and cyst formation." (PMID 33158935, 2020). "It was also revealed that FGF10 exposure decreased cyst thickness, implying a potential role of this essential signaling molecule for cell shape regulation." (PMID 39213428, 2024). "When added to human lung explants, FGF10 inhibits branching but favors cyst formation." (PMID 33158935, 2020). "Small explants (<100 μm) of the distal epithelium were grown in Matrigel with various concentrations of FGF10 for 18 h, and the ERK activity of each cyst was measured." (PMID 39213428, 2024). "We identified changes in gene expression related to cyst growth such as components of MAPK (e.g. Map3k12, Fgf10, Prkcb, Traf2) and TGF-β (e.g. Pitx2) signaling that were up-regulated in the Pkd1-/- animals." (PMID 21518438, 2011). "Limb epithelium placed outside the Fgf10 expression zone failed to branch and formed a cyst." (PMID 24167707, 2013).
myocardial infarction (5 papers, 2010 to 2025). Gross necrosis of the myocardium, as a result of interruption of the blood supply to the area, as in coronary thrombosis. "Using a mouse model of myocardial infarction, researchers have directly injected exogenous FGF10 into the ischemic zone to increase its level, thereby reducing myocardial damage and restoring heart function." (PMID 41239804, 2025). "There is substantial evidence that FGF10 enhances cardiac repair after myocardial infarction by inhibiting apoptosis, improving fibrosis, and promoting myocardial regeneration." (PMID 41239804, 2025). "A long term in vivo study is required to verify the roles of FGF-10-guided ES cell differentiation in aiding cardiac repair after myocardial infarction." (PMID 21203390, 2010). "Previous studies have shown that FGF10 regulates the YAP pathway, which is involved in cardiomyocyte apoptosis and myocardial regeneration and repair after myocardial infarction." (PMID 41239804, 2025).